PRR7 (proline rich 7, synaptic)
Description:
Acts as a synapse-to-nucleus messenger to promote NMDA receptor-mediated excitotoxicity in neurons in a JUN-dependent manner (By similarity). Inhibits ubiquitination-mediated degradation and promotes phosphorylation and transcriptional activity of transcription factor JUN. Might play a redundant role in the regulation of T cell receptor signaling. Might promote apoptosis in T cells.
Synonyms: MGC10772
Tractability: Antibody: UniProt places it where antibodies can reach, with high confidence; its Gene Ontology location is reachable by antibodies, with high confidence; UniProt predicts a signal peptide or a membrane-spanning region; the Human Protein Atlas places it where antibodies can reach.
Gene: Protein-coding gene on chromosome 5 (177,446,445 to 177,456,291, forward strand). Ensembl gene ENSG00000131188.
Subcellular location: Cell membrane; Postsynaptic cell membrane; Postsynaptic density membrane; Cytoplasm, perinuclear region; Synapse; Cell projection, dendrite; Nucleus
Subcellular location (Human Protein Atlas): Cytosol; Nucleoplasm; Plasma membrane
Gene Ontology:
Molecular function: long-chain fatty acid binding; protein binding; protein tyrosine kinase binding; ubiquitin-like protein ligase binding; protein-containing complex binding
Biological process: positive regulation of apoptotic process; regulation of transcription by RNA polymerase I; postsynapse to nucleus signaling pathway; T cell differentiation
Cellular component: cytosol; nucleoplasm; nucleus; perinuclear region of cytoplasm; plasma membrane; synapse; postsynaptic density membrane; postsynaptic density, intracellular component; postsynaptic membrane; dendrite; glutamatergic synapse; neuron projection; postsynaptic density
Genetic constraint (gnomAD): Loss-of-function variants: 8 observed, 10.27 expected, observed/expected ratio (o/e) 0.78, 90% interval 0.46 to 1.4. The synonymous counts are far from expectation, so gnomAD's model fits this gene poorly and the ratio says little. Missense variants: 396 observed, 304.89 expected, observed/expected ratio (o/e) 1.3, 90% interval 1.2 to 1.41. Synonymous variants: 221 observed, 151.83 expected, observed/expected ratio (o/e) 1.46, 90% interval 1.3 to 1.63.
Homologues: Orthologues: chimpanzee PRR7 (100% identical), macaque PRR7 (99% identical), dog PRR7 (96% identical), guinea pig PRR7 (96% identical), mouse Prr7 (95% identical), pig PRR7 (95% identical), rat Prr7 (88% identical), tropical clawed frog PRR7 (48% identical). Paralogues in human: WBP1L (18% identical), WBP1 (15% identical).
Diseases named in the same sentence as PRR7 in open-access papers:
PRR7 is named in the same sentence as 16 diseases in open-access papers, as found by Europe PMC text mining. Sharing a sentence is not in itself a finding about the gene and the disease. The quoted sentences say what the papers report.
Arrhythmia (2 papers, 2014 to 2024). Any cardiac rhythm other than the normal sinus rhythm. "Consistent with previous reports, both null mutants, elf3-1 and elf3-4, displayed arrhythmia with reduced levels of CCA1::LUC and LHY::LUC and high levels of TOC1::LUC, GI::LUC, PRR7::LUC, and PRR9::LUC, compared to Bay-0." (PMID 24867215, 2014).
Anxiety (1 paper, 2022). Intense feelings of nervousness, tension, or panic often arise in response to interpersonal stresses. "A previous study revealed that mice with a constitutive functional deletion of miR-379-410 exhibited heightened sociability and anxiety, along with increased excitatory transmission in hippocampal excitatory neurons and up-regulation of Prr7." (PMID 36150742, 2022).
breast carcinoma (1 paper, 2019). "After FDR correction, four of these genes were individually significantly associated with disease-free survival, including the steroidogenic enzyme CYP11A; LGR6, a WNT regulator and implicated in breast cancer; and PRR7, a central regulator of CLOCK." (PMID 30120411, 2019).
colorectal cancer (1 paper, 2022). A primary or metastatic malignant neoplasm that affects the colon or rectum. "Thus, LINC00242 and LINC02535 affect the proliferation and apoptosis of gastric cancer, PRR7-AS1is involved in colorectal cancer metabolism, and LINC01146 and MIR3142HG in inflammation." (PMID 35486664, 2022).
depressive disorder (1 paper, 2023). A melancholy feeling of sadness and despair. "Additionally, we identified significant methylation sites in individual genes that have been previously linked to neuropsychiatric disorders, including depressive disorders (FAM172A), internalizing disorders (SDK1), and neurodegenerative disorders (PRR7)." (PMID 37634000, 2023).
experimental autoimmune encephalomyelitis (1 paper, 2016). An autoimmune demyelinating disease of the central nervous system that is produced experimentally in animals by the injection of homogenized brain or spinal cord in Freund's adjuvant. "In addition, T cell effector functions (activation, migration, and reactivation) were normal following induction of experimental autoimmune encephalomyelitis (EAE) in Prr7 knockout mice." (PMID 27657535, 2016).
hyperuricemia (1 paper, 2022). An abnormally high level of uric acid. "Of note, prr7, which was shown to enhance the stability of c-Jun, and jund, another component of the c-Jun subfamily within the AP-1 complex, were both found to be transcriptionally upregulated by hyperuricemia." (PMID 36504525, 2022).
Listeria monocytogenes infection (1 paper, 2016). "Importantly, Prr7 knockout mice retained the capacity to mount a protective immune response when challenged with Listeria monocytogenes infection in vivo." (PMID 27657535, 2016). "The results of the Listeriosis infection model suggest that Prr7 deficiency does not impair the ability of the mouse immune system to cope with Listeria monocytogenes infection." (PMID 27657535, 2016).
lymph node metastasis (1 paper, 2022). "Significant elevations of PRR7 mRNA expression correlate with lymph node metastasis." (PMID 35681785, 2022).
tumor (2 papers, 2021 to 2022). "Additionally, high levels of RECQL4, MXD3, and PRR7 mRNA expression are associated with advanced tumor stages." (PMID 35681785, 2022).
PRR7 also shares sentences with these, for which no sentence is quoted: Autoimmunity (1 paper); cancer (1); gastric cancer (1); infection (1); internalizing disorder (1); prostate carcinoma (1).